PPARA (peroxisome proliferator activated receptor alpha)
Diseases named in the same sentence as PPARA in open-access papers (continued):
Sharing a sentence is not in itself a finding about the gene and the disease.
Insulin resistance (continued). "It was found that Pgc-1α promoted insulin resistance in the liver through a PPARα-dependent activation of the mammalian tribbles homolog TRB-3, a fasting-inducible inhibitor of the serine-threonine kinase Akt/PKB." (PMID 33348802, 2020). "For instance, it was previously shown that hepatic Pparα inversely correlated with insulin resistance and NASH severity." (PMID 32046285, 2020). "Our studies have shown that the BVRA isoform is essential for protection from hepatic steatosis and insulin resistance through its positive regulation of nuclear receptor peroxisome proliferator-activated receptor-α (PPARα)." (PMID 32131495, 2020). "It regulates lipid homeostasis and insulin resistance by regulating peroxisome proliferators-activated receptor α (PPARα)/PGC1-α and GLUT4, respectively." (PMID 30658634, 2019). "From metabolic disease, the resolution of insulin resistance by PPARγ and combined PPARα/γ agonists, as well as long-term outcome in patients with type II diabetes, we learned a lot on simultaneous PPARα/γ stimulation." (PMID 30424016, 2018). "NASH seriousness, visceral adiposity, and insulin resistance were negatively correlated with human liver PPARα gene expression while adiponectin was positively related." (PMID 30428868, 2018). "Regarding the role of PPARα controlling fatty acids oxidation, its downregulation has been related with insulin resistance." (PMID 30322196, 2018). "This study demonstrated that MHY3200 improved hepatic lipid accumulation, insulin resistance, and inflammation through increased PPARα activation in HFD rats." (PMID 30115876, 2018). "PPARα activation has also been shown to improve the overall proatherosclerotic plasma lipid profile and to have beneficial effects on insulin resistance and inflammation." (PMID 30622558, 2018). "It has been previously reported that ursolic acid improves hepatic insulin resistance by stimulating the expression of peroxisome proliferator-activated receptors α (PPARα)." (PMID 28420354, 2017). "AMPK- and PPARα-specific siRNAs significantly abrogated the suppressive effects of PDX on palmitate-induced insulin resistance and inflammation." (PMID 28469249, 2017). "In general, PPARα activation mediates lipid oxidation and reduces ectopic lipid storage, thereby counteracting insulin resistance." (PMID 27153842, 2016). "Recently, it was found that human liver PPARα gene expression correlates negatively with the severity of steatohepatitis and with measures of insulin resistance." (PMID 26449539, 2015). "It has recently been shown that insulin resistance drives the cardiac mitochondrial biogenesis regulatory program via PPARα, where activation was increased due to increased fat uptake and oxidation." (PMID 24447392, 2014). "Another study showed that hepatic PPARα activation led to glucocorticoid-induced insulin resistance and hypertension via an afferent vagal nerve pathway." (PMID 25511156, 2014). "It has been previously shown that PPARα agonist can improve insulin resistance, and decrease the fasting blood glucose level in obese mice." (PMID 24147098, 2013). "We demonstrate that combined treatment by T0901317, a potent activator of LXR, and fenofibrate, an agonist of PPARα, alleviated insulin resistance and improved glucose tolerance." (PMID 23762402, 2013). "Apart from that, PPARα has the ability to prevent insulin resistance in diabetic due to the increase of fatty acids oxidation in pancreas, muscle and liver." (PMID 23762147, 2013). "Treatment of high fat diet-induced obese mice with T0901317, an LXR activator, or fenofibrate, the PPARα agonist, or in combination alleviated insulin resistance and improved glucose tolerance." (PMID 23762402, 2013). "In some studies, the activation of PPARα and subsequent enhanced expression of the PPARα target gene, which increases fatty acid oxidation, were observed during insulin resistance and diabetes." (PMID 23057715, 2012).
Insulin resistance (continued). "Low-grade inflammation is considered to be an important mechanism in insulin resistance, and the lipid metabolic regulators PPARα, PPARγ, as well as PGC-1α have been shown to play a role in the regulation of insulin sensitivity." (PMID 23251491, 2012). "Third, PPARα activation ameliorates systemic insulin resistance, lipid abnormality, energy homeostasis, hypertension, and vascular injuries." (PMID 22675338, 2012). "Previous studies showed that Pparα null mice become more obese on a high-fat diet than wild-type mice, but are resistant to dietary fat-induced insulin resistance." (PMID 18457598, 2008). "PPARα expression is inversely correlated with the severity of metabolic dysfunction-associated steatohepatitis ([MASH]; formerly non-alcoholic steatohepatitis [NASH]), visceral obesity, and insulin resistance in humans." (PMID 41438090, 2025). "Taken together, these findings suggest that FAM3A may promote lipid accumulation in muscle and ameliorate insulin resistance and inflammation by enhancing PPARα signaling." (PMID 41353211, 2025). "Recent studies have demonstrated that PPAR agonists (PPARα and PPARγ) reduce body weight, ameliorate insulin resistance, induce the browning of beige adipocytes, enhance both UCP1‐dependent and independent thermogenesis, and improve mitochondrial metabolism in murine models." (PMID 40666825, 2025). "Moreover, the PGC-1β/PPARα pathway is involved in regulating cardiac metabolism, particularly in conditions of insulin resistance." (PMID 39125938, 2024). "Phytol plays a promising role in the management of insulin resistance by modulating the transcription activity of peroxisome proliferator-activated receptor alpha and retinoid X receptor, increasing the serum adiponectin level and decreasing the level of TNF-α." (PMID 39479139, 2024). "Similarly, dual-acting PPARα/γ agonists (glitazars), such as tesaglitazar, also beneficially affected the glucose metabolism, insulin resistance and atherogenic dyslipidaemia in patients with type 2 diabetes." (PMID 38627464, 2024). "Furthermore, PPARα contributes to the amelioration of insulin resistance by reducing the dysregulation of intracellular insulin signaling cascade and protein expression." (PMID 38276548, 2024). "Moreover, PAEs can selectively regulate PPARα and in turn affect lipid modulation and glucose homeostasis, resulting in insulin resistance, which also contributes to the development of diabetes." (PMID 35578291, 2022). "In this regard, blocking the inhibitory effect of PCTP/ACOT13 and leucine might enable insulin to suppress PPARa activity for longer and avoid insulin resistance." (PMID 35269927, 2022). "How PPARα affects diabetes particularly insulin resistance needs more evidence." (PMID 36589809, 2022). "A recent study has found that the activation of the PI3K-Akt signaling pathway could inhibit the expression of SREBP1c and PPARα protein, finally resulting in lipid metabolism disorders and insulin resistance, promoting the process of NAFLD." (PMID 35795275, 2022). "PPARα mainly influences fatty acid metabolism, and its activation lowers lipid levels, while PPARγ is mostly involved in the regulation of adipogenesis, the energy balance, and lipid biosynthesis, and its activation affects insulin resistance." (PMID 36501129, 2022). "Studies have shown that PPARα activation in obese and insulin-resistant animal models can effectively stimulate fatty acid oxidation and inhibit the lipid accumulation in liver and muscle tissues, improving insulin sensitivity and insulin resistance." (PMID 34443619, 2021). "Moreover, they can improve insulin resistance through the modulation of peroxisome proliferator-activated receptor alpha." (PMID 34202690, 2021).
Insulin resistance (continued). "The expression of PPARα is increased in pathological conditions that accompanied with insulin resistance and in diabetes mellitus where metabolisms are impaired, suggesting its potential role in enhancing fatty acid transport and oxidation observed in diabetic hearts." (PMID 33397369, 2021). "Indeed, it was demonstrated that PPARα-null mice are protected from insulin resistance induced by a high-fat diet." (PMID 32235294, 2020). "Finally, activation of PPARα can reduce the accumulation of deleterious lipids and lead to amelioration of hepatic insulin resistance and oxidant/ER stress." (PMID 33177546, 2020). "However, PPARα KO mice are protected from high-fat diet-induced insulin resistance, which is most likely because of the development of increased adiposity." (PMID 32708786, 2020). "On the other hand, melatonin administration could improve the degree of insulin resistance, which could be related to increased fatty acid oxidation via AMPKα/PPARα signaling pathway activation." (PMID 33150187, 2020). "Due to the fact that many diabetic patients suffer from atherogenic lipid abnormalities and insulin resistance, ligands that may stimulate both PPARα and PPARγ could be efficaciously used in obese patients with type 2 diabetes." (PMID 33255206, 2020). "Thus, the present study investigated the effects of MHY3200, a novel PPARα agonist, on lipid accumulation-independent ER stress and insulin resistance-induced inflammation in the livers of rats with high-fat diet-induced obesity." (PMID 30115876, 2018). "Interestingly, PPARα also governs expression in hepatocytes of tribbles pseudokinase 3 (Trib3), a putative protein kinase that promotes insulin resistance in mice and humans." (PMID 28793934, 2017). "In liver, however, PGC-1α may also promote insulin resistance via co-activation of PPARα and induction of Trible-391." (PMID 28084425, 2017). "PPARα is predominantly expressed in tissues with a high catabolic activity for fatty acid; it plays a crucial role in the development of insulin resistance and orchestrates glucose homeostasis and in lipid catabolism and homeostasis by stimulating fatty acid β oxidation." (PMID 27347932, 2016). "Therefore, using a PPARδ specific ligand, GW0742, can activate the protective effects from hypertriglyceridemia and insulin resistance as what PPARα and PPARγ do but alternatively prevents the sequel of edema and fluid retention induced by PPARγ." (PMID 27519769, 2016). "Therefore, it is possible that therapeutic drugs for insulin resistance, such as AMPK activator or PPARα/γ dual agonist, have the potential to become anti-aging agents by ameliorating insulin resistance." (PMID 25239110, 2014). "Thus, compounds that stimulate both PPARα and PPARγ (dual PPARα/γ agonists) should additively improve both lipid and glucose abnormalities in animal models and human subjects with insulin resistance (IR) and/or type 2 diabetes (T2DM)." (PMID 23226761, 2012). "Regarding mechanisms by which DHEA may reverse insulin resistance, one possibility is by activation of PPARα for which DHEA is a ligand." (PMID 21566261, 2011). "From the viewpoint of PPARα activation improving insulin sensitivity, the observations of PPARα agonists /activators downregulating TF expression also likely point to positive TF function(s) in insulin resistance involving inflammatory diabetes development." (PMID 21941675, 2011). "PPARα also regulates insulin resistance and diabetes due to visceral obesity." (PMID 20871824, 2010). "The presence of the PPARα 162Val allele was associated with insulin resistance, but not with liver damage in NAFLD." (PMID 20825652, 2010). "The presence of the PPARα 162Val allele (prevalence 57%), but not of the PPARγ2 12Ala allele (prevalence 18%), was associated with higher insulin resistance (HOMA-IR index 4.71 ± 3.8 vs. 3.58 ± 2.7, p = 0.026), but not with hyperglycemia." (PMID 20825652, 2010).
Insulin resistance (continued). "With regard to our study this might suggest that an elevated activation of Pparα in the small intestine can contribute to development of insulin resistance on a high-fat diet." (PMID 18457598, 2008). "In addition, animal studies suggest that that the activation of PPARα improved the insulin resistance that was triggered by the excessive production and accumulation of lipids." (PMID 16091142, 2005). "Therefore, we hypothesized that HEP might mitigate liver lipid deposition via activating PPARα, thereby alleviating insulin resistance." (PMID 39942052, 2025). "Thus, induction of insulin resistance by impaired BCAA metabolism may partly contribute to aberrant upregulation of PPARα and ATGL in cardiomyocytes." (PMID 36802195, 2023). "Moreover, PPARα knockout was reported to rescue obese mice from insulin resistance." (PMID 36835365, 2023). "In addition, administration of naringen into a diabetic 53-year-old African American female (a case study) showed that naringenin exerted its regulatory effects on insulin resistance and metabolic rate via activation of PPARα and PPARγ, leading to promotion of UCP1 and CPT1β." (PMID 36092543, 2022). "Therefore, exercise in pre-diabetic patients may offer metabolic benefits by raising HO-1, upregulating adiponectin and bilirubin levels, enhancing insulin signaling, activating PPARα pathways, and thus, decreasing insulin resistance." (PMID 35204062, 2022). "The present study demonstrated that Suc feeding did not cause insulin resistance in PPARα−/− mice." (PMID 36140300, 2022). "Therefore, PGC-1α promotes liver insulin resistance through PPARα-dependent induction of TRIB3." (PMID 30987128, 2019). "Additionally, increased levels of NEFA in response to insulin resistance may activate transcription factors such as PPARα in the liver, which could also contribute to the regulation of genes such as G6pc, Angplt4, and Insig2." (PMID 30532187, 2018). "There are three PPAR isoforms with different pharmacological activities; PPARα plays a key role in lipid metabolism, whereas PPARγ and PPARδ are critical players in regulating energy metabolism in adipose tissue and muscle, as well as being targets for the treatment of insulin resistance." (PMID 24460800, 2014). "Therefore, by activating PPARα, PPARδ, and PPARγ together and reducing TG in skeletal muscles, bezafibrate might improve glucose intolerance and insulin resistance in skeletal muscle." (PMID 25360162, 2014). "Results indicated that the 162Val SNP, present in 57% of the patients, was associated with increased insulin resistance in patients but not in controls, suggesting a possible interaction between liver fat and the PPARα 162Val allele in the pathogenesis of insulin resistance." (PMID 20825652, 2010). "Fenofibrate prevents adipocyte hypertrophy and insulin resistance by increasing FA β-oxidation and intracellular lipolysis from visceral adipose tissue, showing that PPARα may be one of the major factors leading to decreased adipocyte size and improved insulin sensitivity." (PMID 20871824, 2010). "However, in sharp contrast, hepatic insulin resistance was observed in PPARα−/− mice." (PMID 20936117, 2010). "While observations in rodents could have pointed to risks for human treatment with PPARα agonists (e.g., hepatocarcinogenesis, skeletal muscle insulin resistance, and myopathy) it has been shown that in humans, PPARα activation is a useful therapeutic target in treating metabolic disorders." (PMID 20847941, 2010). "In light of those results, PPARγ agonists appear to becompelling drugs for the prevention of liver injury related to insulin resistance.PPARα could be involved in fibrogenesis through adiponectin activation, as thisadipokine could have antifibrogenic properties." (PMID 19390649, 2009).
Insulin resistance (continued). "Results: miR-122 was found to negatively regulate genes involved in lipid metabolism, insulin signaling, and inflammatory pathways, including PPARGC1A, PPARA, LPL, TLR4, and HMGCR, contributing to insulin resistance and liver dysfunction." (PMID 41595656, 2026). "Under diabetic conditions, the activation of Peroxisome Proliferator-Activated Receptor Alpha (PPARα) can attenuate the cGAS-STING signaling pathway, leading to reduced inflammation and insulin resistance." (PMID 41020872, 2025). "PPARα activation increases PEPCK and G6Pase expression, leading to hyperglycemia and insulin resistance." (PMID 41440753, 2025). "Preclinical studies in mice have shown that both genetic modulation and protein concentrations of PPARα and PGC-1α are impaired in insulin resistance conditions, leading to an impairment of the insulin–cardiac axis." (PMID 39125938, 2024). "Interestingly, the downregulation of PPARα and PPARγ, such as the one we highlighted in our model, could be related to the accumulation of lipid droplets within hepatocytes, also contributing to the insulin resistance reported in DS individuals." (PMID 38942607, 2024). "As a transcriptional corepressor, NCOR1 further represses the PPARα and RXR-mediated PPARα response genes, such as FGF21 expression, thus affecting fatty acid oxidation and ketogenesis, which finally result in insulin resistance." (PMID 38397480, 2024). "The PPARα and PPARγ vastly function to reduce inflammation, while PPAR-beta(β) is a potential target for the treatment of insulin resistance." (PMID 36164476, 2022). "In perfect agreement with our model’s predictions, a mechanistic study showed that chamomile ameliorates insulin resistance through transcriptional stimulation of PPARG and PPARA in the adipose tissue and liver, respectively." (PMID 36160451, 2022). "AdipoRon exerted actions on muscle and liver cells by activating the PPARα and AMPK pathways and ameliorated insulin resistance in diabetic mice." (PMID 34204799, 2021). "Based on the pathway enrichment analysis, targets (INSR, PTPN1, PPARA, PPARG) from two of the most significant pathways, Insulin resistance, and PPAR signaling pathway, were selected for further experimental validation." (PMID 34579756, 2021). "PPARα was shown to bind to and antagonize FOXO1 in hepatic apoC-III expression, suggesting the importance of FOXO1 deregulation in the pathology of insulin resistance and hypertriglyceridemia." (PMID 32182991, 2020). "While biliverdin reductase-A (BVRA) protected against hepatic steatosis via PPARα activation, BVRA knockout mice on a HFD were glucose insensitive and BVRA was lower in obese humans with insulin resistance." (PMID 31577826, 2019). "There is an up-expression of PPARα target genes in the PBMCs of NAFLD patients, possibly leading to changes in β-oxidation and insulin resistance." (PMID 30428868, 2018). "PPARα is also expressed in the WAT, where its activation elicits systemic effects in rodents by decreasing adiposity and ameliorating the insulin resistance in obese mouse models." (PMID 30037087, 2018). "In conclusion, our results demonstrate that PDX ameliorates insulin resistance and inflammation and stimulates fatty acid oxidation through AMPK- and PPARα-mediated pathways in skeletal muscle." (PMID 28469249, 2017). "In the current study, we explored the effects of PDX on hyperlipidemia-induced insulin resistance and inflammation through AMP-activated protein kinase (AMPK) and peroxisome proliferator-activated receptor α (PPARα)." (PMID 28469249, 2017). "Overall, the dual activation of PPARα and FXR appears to completely prevent FF-induced insulin resistance not only in the liver, but also in skeletal muscle, further highlighting the potential of this prospective therapeutic approach." (PMID 28406477, 2017). "GLUT4 is regulated by AMPK and PPARα, and considerable evidence supports the AMPK-mediated process protects against insulin resistance." (PMID 24879081, 2014).